RNU6-1127P (RNA, U6 small nuclear 1127, pseudogene)
Gene: Small nuclear RNA gene on chromosome 3 (119,341,834 to 119,341,940, reverse strand). Ensembl gene ENSG00000207310.
Homologues: Orthologues: chimpanzee U6 (98% identical), macaque U6 (96% identical), guinea pig U6 (86% identical), dog U6 (80% identical), dog U6 (79% identical). Paralogues in human: RNU6-11P (90% identical), RNU6-1274P (90% identical), RNU6-37P (90% identical), RNU6-43P (90% identical), RNU6-25P (89% identical), RNU6-1 (88% identical), RNU6-15P (88% identical), RNU6-2 (88% identical), RNU6-23P (88% identical), RNU6-38P (88% identical), RNU6-3P (88% identical), RNU6-4P (88% identical), and 1285 more.